FAAP20 (FA core complex associated protein 20)
Description:
Component of the Fanconi anemia (FA) complex required to recruit the FA complex to DNA interstrand cross-links (ICLs) and promote ICLs repair. Following DNA damage recognizes and binds 'Lys-63'-linked ubiquitin generated by RNF8 at ICLs and recruits other components of the FA complex. Promotes translesion synthesis via interaction with REV1.
Synonyms: C1orf86; FP7162; FLJ31031
Tractability: PROTAC: ubiquitination databases record sites on it.
Gene: Protein-coding gene on chromosome 1 (2,184,461 to 2,212,720, reverse strand). Ensembl gene ENSG00000162585.
Subcellular location: Nucleus; Chromosome
Subcellular location (Human Protein Atlas): Nucleoplasm; Cell Junctions; Nuclear bodies
Pathways (Reactome):
DNA Repair: Fanconi Anemia Pathway
Immune System: PKR-mediated signaling
Gene Ontology:
Molecular function: K63-linked polyubiquitin modification-dependent protein binding; polyubiquitin modification-dependent protein binding; protein binding; ubiquitin-modified protein reader activity; ubiquitin binding
Biological process: DNA damage response; interstrand cross-link repair; translesion synthesis
Cellular component: chromatin; chromosome; Fanconi anaemia nuclear complex; nuclear body; nucleoplasm; nucleus; cytosol
Genetic constraint (gnomAD): Loss-of-function variants: 15 observed, 17.24 expected, observed/expected ratio (o/e) 0.87, 90% interval 0.58 to 1.34. The upper end of that interval is the gene's LOEUF score, 1.34, which puts it in group 5 of 6, group 1 being the genes least tolerant of losing a copy. Missense variants: 274 observed, 239.62 expected, observed/expected ratio (o/e) 1.14, 90% interval 1.03 to 1.26. Synonymous variants: 133 observed, 107.27 expected, observed/expected ratio (o/e) 1.24, 90% interval 1.08 to 1.43.
Homologues: Orthologues: chimpanzee FAAP20 (97% identical), pig FAAP20 (59% identical), mouse Faap20 (54% identical), dog FAAP20 (52% identical), rat Faap20 (51% identical).
Diseases named in the same sentence as FAAP20 in open-access papers:
FAAP20 is named in the same sentence as 16 diseases in open-access papers, as found by Europe PMC text mining. Sharing a sentence is not in itself a finding about the gene and the disease. The quoted sentences say what the papers report.
Fanconi anemia (7 papers, 2014 to 2025). Fanconi anemia (FA) is a hereditary DNA repair disorder characterized by progressive pancytopenia with bone marrow failure, variable congenital malformations and predisposition to develop hematological or solid tumors. "FAAP20, or Fanconi anemia-associated protein 20, is a 20 kDa protein that is a member of the Fanconi anemia (FA) pathway of DNA repair." (PMID 37620397, 2023). "FAAP20 is a Fanconi anemia (FA) protein that associates with the FA core complex to promote FANCD2/FANCI monoubiquitination and activate the damage response to interstrand crosslink damage." (PMID 37620397, 2023). "Here, we demonstrate that SCFFBW7 regulates the stability of FAAP20, a critical component of the Fanconi anemia (FA) DNA interstrand cross-link (ICL) repair pathway." (PMID 27232758, 2016). "In particular, the UBZ domain of FAAP20 (FAAP20-UBZ), a member of the Fanconi anemia core complex, seems to recognize K63-linked ubiquitin chains, in order to recruit the complex to DNA interstrand crosslinks and mediate DNA repair." (PMID 25799058, 2015). "The ubiquitin-binding capacity of the FAAP20 UBZ is required for recruitment of the Fanconi anemia complex to interstrand DNA crosslink sites and for interaction with the translesion synthesis machinery." (PMID 25414354, 2014). "FAAP20 is an integral component of the Fanconi anemia core complex that mediates the repair of DNA interstrand crosslinks." (PMID 25414354, 2014).
breast carcinoma (4 papers, 2019 to 2024). "Additionally, a recent study has demonstrated that FAAP20 is a strong prognostic risk factor for breast cancer development where high FAAP20 expression level was associated with higher T stage and worse overall prognosis in human breast cancer patients." (PMID 37620397, 2023). "Among breast cancer subtypes, the top eight mutational rates were MAD2L2/FANCV (37.5%), FANCI (32%), ATR (32%), FAAP20 (30%), FAAP100 (28%), SLX4 (27%), FANCT (27%), and BRIP1 (26%) in breast invasive carcinoma NOS." (PMID 39421870, 2024). "The hazard ratio of other six genes (FAAP20, RRM2B, UBE2A,RAD50,MRE11, and RPA3) was >1, regarded as risk factors in developing breast cancer." (PMID 36713553, 2022). "The prognostic value of FAAP20 expression in breast cancer progression suggests that FAAP20 protein could be a promising target in breast cancer treatment." (PMID 37620397, 2023). "In total, 11 DNA repair genes (UBE2A, RBBP8,RAD50, FAAP20, RPA3, ENDOV, DDB2, UBE2V2,MRE11, RRM2B, andPARP3) were preserved as prognostic genes to estimate risk score, which was applied to establish the prognostic model and stratified breast cancer patients into two groups with high or low risk." (PMID 36713553, 2022). "Thus, based on our findings, we determined whether pharmacological inhibition of PIN1 is sufficient to disrupt the FA pathway via FAAP20 destabilization in breast cancer, where high levels of PIN1 have been correlated with aggressiveness and chemoresistance." (PMID 30789902, 2019). "A total of 11 DNA repair genes, namely, UBE2A, RBBP8,RAD50, FAAP20, RPA3, ENDOV, DDB2, UBE2V2,MRE11, RRM2B, andPARP3, were involved in the prognostic model for breast cancer patients." (PMID 36713553, 2022). "In this study, however, FANCA did not rank as a prognostic factor in breast cancer which strengthens the importance of FAAP20’s repair roles in cancer cells." (PMID 37620397, 2023).
cervical cancer (1 paper, 2016). A primary or metastatic malignant neoplasm involving the cervix. "PMS1, RAD54B, FAAP20 and BRCA1 exhibited almost uniform hyper- or hypomethylation in the cervical cancer samples." (PMID 27683114, 2016).
colorectal cancer (1 paper, 2016). A primary or metastatic malignant neoplasm that affects the colon or rectum. "Moreover, FBW7 knockout in HCT116 colorectal cancer cells increased the cellular FAAP20 levels and half-life compared with wild-type cells without altering FAAP20 mRNA levels." (PMID 27232758, 2016).
nephritis (1 paper, 2015). Inflammation of renal tissue. "Other increased mRNAs linked to the presence of nephritis were C1orf86/FAAP20, coding for a DNA repair factor, and LINC00339, an uncharacterized noncoding RNA." (PMID 26544975, 2015).
tumor (3 papers, 2016 to 2023). "As such, it is counterintuitive that FBW7 limits the expression of FAAP20, a core component of DNA repair machinery that is generally considered to function as a tumor suppressor." (PMID 27232758, 2016). "This may indicate that the interaction of FAAP20 with FANCA functions as a tumor suppressor specifically in TNBC, which could involve the SSA function of FAAP20/FANCA that we have observed." (PMID 37620397, 2023). "Interestingly, previous studies implicated various FA complex proteins, such as FANCM, MHF1, FAAP20 and FAAP24, in tumor cell survival after DNA damage." (PMID 26625197, 2016). "Furthermore, overexpression of FBW7 F-box deletion or tumor-derived R505C WD40 mutant was not as potent as wild-type in decreasing the FAAP20 levels, suggesting that intact F-box and WD40 domains are required for efficient FAAP20 degradation, which is similar to other known substrates." (PMID 27232758, 2016).
cancer (2 papers, 2018 to 2023). A tumor composed of atypical neoplastic, often pleomorphic cells that invade other tissues. "Nevertheless, our experiments in FAAP20-deficient cancer cells show that FAAP20’s ability to support HDR repair pathways leads to its ability to maintain cell growth and proliferation during IR treatment, PARPi, and RAD52i." (PMID 37620397, 2023). "This further strengthens a role for FAAP20 in HR as loss of other HR factors are also shown to cause sensitivity to RAD52 inhibition (RAD52i) in cancer cells." (PMID 37620397, 2023). "We also see that FAAP20 supports cellular colony formation and proliferation, which corresponds with its strong HR function and may underlie the ability of FAAP20 to affect cancer outcomes and therapy resistance." (PMID 37620397, 2023). "However, FAAP20 has an established prognostic value associated with its protein expression in multiple cancer types, which warrants a closer look at its roles in genome maintenance and stability." (PMID 37620397, 2023). "Despite the significant clinical outcome associated with FAAP20-mutated cancers, genetic screening for FAAP20 patient variants is very uncommon, warranting increased attention and testing of FAAP20’s expression status in aggressive cancers." (PMID 37620397, 2023). "Additionally, FAAP20 mutation in cancer causes HDR deficiency which is highly prognostic in itself." (PMID 37620397, 2023). "According to The Human Protein Atlas, FAAP20 has differential prognostic status, depending on the cancer tissue type of origin, where its overexpression is unfavorable in liver cancer but favorable in pancreatic cancer." (PMID 37620397, 2023). "The identification of FAAP20 as a major HDR factor strengthens the notion that FAAP20 has significant diagnostic and prognostic value in cancer." (PMID 37620397, 2023). "FAAP20’s ability to influence cancer outcome in a cell-type-dependent manner indicates an unrealized and potentially powerful cellular role of FAAP20." (PMID 37620397, 2023). "To see how FAAP20’s role in HDR contributes to cancer cell proliferation, we performed clonogenic survival assays in three cancer cell lines: HeLa, MIA PaCa-2, and U2OS." (PMID 37620397, 2023). "It is likely that the strong dependency on FAAP20 in clonogenic survival that we observe is specific to cancer cells that depend on alternative DSB repair subpathways to support HR and replication fork stability." (PMID 37620397, 2023). "Together, our work places a focus on FAAP20 in supporting repair of DSBs, which has future applications in understanding cancer growth and therapy resistance." (PMID 37620397, 2023). "Like other homology-directed repair factors, FAAP20 loss causes a reduction in nuclear RAD51 Irradiation-induced foci; and sensitizes cancer cells to ionizing radiation and PARP inhibition." (PMID 37620397, 2023). "This discrepancy emphasizes the influence of cell type when evaluating the importance of FAAP20’s repair roles and suggests the ability for selective therapeutic targeting of cancer cells over non-cancer cells by modulating FAAP20 activity." (PMID 37620397, 2023). "Not only does FAAP20’s role as an HDR factor implicate its prognostic value in cancer development but may also be predictive in tumorigenesis." (PMID 37620397, 2023). "The strong role for FAAP20 in HR and cell proliferation compared to FANCA elucidates repair mechanisms that can be preferentially utilized by dividing cancer cells." (PMID 37620397, 2023).
FAAP20 also shares sentences with these, for which no sentence is quoted: anemia (1 paper); diabetes (1); heart disease (1); heroin addiction (1); invasive carcinoma (1); lung carcinoma (1); lung squamous cell carcinoma (1); meningioma (1); triple-negative breast carcinoma (1).